TNFAIP1 (TNF alpha induced protein 1)
Diseases named in the same sentence as TNFAIP1 in open-access papers (continued):
Sharing a sentence is not in itself a finding about the gene and the disease.
tumor (16 papers, 2007 to 2023). "TNF-α-induced protein 1 (TNFAIP1; B12) gene is a highly conserved gene in several species and is known as a tumor suppressor gene." (PMID 37760246, 2023). "Caudatin inhibits the tumor progression by targeting the cytochrome c/caspase and TNFAIP1/NF-κB signaling pathways, as well as reducing the clonogenicity and viability of uterine cancerous cells." (PMID 35264951, 2022). "Our findings highlight a crucial role of TNFAIP1-induced RhoB degradation in regulating tumor inflammatory response." (PMID 33553178, 2021). "Future study will be performed to elucidate the effect of TNFAIP1-mediated RhoB degradation on tumor inflammatory microenvironment and tumorigenesis." (PMID 33553178, 2021). "A gene highly correlated and specific for the HER-2 tumor subtype is the TNFAIP1 gene (corr = 0.8)." (PMID 33809336, 2021). "TNFAIP1-RhoB axis played a key role in the regulation of tumor inflammatory microenvironment and could be considered as an attractive target for intervention in human cancers." (PMID 33553178, 2021). "It targets and inhibits the expression of TNFAIP1 and TPM1, which are considered to be tumor-suppressive factors and are often used as targets of miRNAs including miR-558 and miR-224, thereby allowing tumor progression." (PMID 37686101, 2023). "Recently, our study reported that the hypomethylation in the CpG islands of the miR-224 promoter region increased the expression of miR-224, and promoted tumor progression and metastasis of NSCLC by targeting SMAD4 and TNFα-induced protein 1 (TNFAIP1)." (PMID 33898432, 2021). "In addition, miR-224 directly targets tumor suppressor, TNFAIP1 and SMAD4, to promote tumor growth both in vitro and in vivo in NSCLC." (PMID 33898432, 2021). "In addition to LATS2, many other tumor suppressors such as PPP6C, DKK1, TNFAIP1 and TP53INP1 are also verified as direct targets of miR-373, implying that miR-373 promotes cell proliferation and tumor growth under certain conditions." (PMID 25990556, 2015). "Moreover, the expression levels of PTX3, TNFAIP6, and TNFAIP8L2 and the genetic alterations of TNFAIP1, TNFAIP6, and STEAP4 greatly impact the clinical outcome of HNC patients, likely by regulating the PI3K-Akt, Ras or other signalling pathways or by regulating tumour immune status." (PMID 34344926, 2021).
cancer (7 papers, 2010 to 2021). A tumor composed of atypical neoplastic, often pleomorphic cells that invade other tissues. "Next, CRL3BTBD9 E3 ubiquitin ligase was determined to suppress cancer cell migration by mediating TNFAIP1 degradation." (PMID 32327643, 2020). "Together, these findings indicate that CRL3BTBD9 targets TNFAIP1 for ubiquitination and degradation in cancer cells." (PMID 32327643, 2020). "Taken together, these findings indicate that Cul3-ROC1 ubiquitin ligase (CRL3) targets TNFAIP1 for ubiquitination and degradation in cancer cells." (PMID 32327643, 2020). "Altogether, our results suggest that BTBD9 suppresses cancer cell migration by promoting TNFAIP1 degradation." (PMID 32327643, 2020). "Taken together, these findings reveal a previously unrecognized mechanism by which the CRL3BTBD9 ubiquitin ligase controls TNFAIP1 degradation to regulate cancer cell migration." (PMID 32327643, 2020). "Taken together, our findings reveal a previously unknown mechanism by which TNFAIP1 is upregulated in cancer and suggest TNFAIP1 as a potential target of cancer cell metastasis." (PMID 32327643, 2020). "Therefore, we speculated that BTBD9 regulated the degradation of TNFAIP1 and affected the metastasis of cancer cells in a RhoA-independent manner." (PMID 32327643, 2020). "Moreover, BTBD9 was shown to suppress cancer cell migration by triggering TNFAIP1 degradation." (PMID 32327643, 2020). "Tumor necrosis factor alpha-induced protein 1 (TNFAIP1) modulates a plethora of important biological processes, including tumorigenesis and cancer cell migration." (PMID 32327643, 2020). "Our analysis of the literature on the members of the TNFAIP1/POLDIP2 SFGM confirmed a previous suggestion regarding its functional integrity and its possible importance in cancers." (PMID 20158880, 2010).
neurodegenerative disease (1 paper, 2016). A disorder of the central nervous system characterized by gradual and progressive loss of neural tissue and neurologic function. "Previous studies described that TNFAIP1 was a pro-apoptotic protein, and apoptosis is a general neuronal death pathway in neurodegenerative diseases which could be triggered by exposure to Aβ." (PMID 27430312, 2016).
neurological disorders (1 paper, 2023). "TNFAIP1 is thought to be associated with tumors and neurological disorders, and, to date, there have been no studies on the function of the TNFAIP1 gene during early development." (PMID 37239365, 2023).
TNFAIP1 also shares sentences with these, for which no sentence is quoted: leukemia (2 papers); endometrial carcinoma (1); lung squamous cell carcinoma (1); malaria (1); microphthalmia (1); PHACE syndrome (1); prostate carcinoma (1); psychosis (1); squamous carcinoma (1); turban tumor syndrome (1); uterine cancer (1).